PHOX2B (paired like homeobox 2B)
Diseases named in the same sentence as PHOX2B in open-access papers (continued):
Sharing a sentence is not in itself a finding about the gene and the disease.
neuroblastoma (continued). "Lung micro-metastatic neuroblastoma (MicroNB) cells show high expression levels of PHOX2B and possess a less malignant and metastatic phenotype than lung macro metastatic neuroblastoma (MacroNB) cells, which hardly express PHOX2B." (PMID 26840262, 2016). "The increased TH expression, a marker for bad prognosis in neuroblastoma, suggested an involvement of PHOX2B in shaping the malignant phenotype of neuroblastoma cells." (PMID 26840262, 2016). "Aberrant methylation of the PHOX2B promoter region accounts for 12.9% of human neuroblastoma cell lines." (PMID 21962230, 2011). "Mutations in the PHOX2B and anaplastic lymphoma kinase (ALK) genes are linked to a predisposition for neuroblastoma." (PMID 20398431, 2010). "PHOX2B, a highly specific marker for neuroblastic tumors, exhibited strong nuclear staining across all primary cultured human neuroblastoma cells, while synaptophysin staining revealed clear cytoplasmic patterns, facilitating individual tumor cell identification." (PMID 40552293, 2025). "This protocol also generated tumors with the highest level of PHOX2B, a marker of neuroblastoma." (PMID 39367051, 2024). "Therefore, we found each protocol can generate tumors that resemble neuroblastoma at the global transcriptomic level but differ in other features such as latency, expression of PHOX2B and subtype of neuroblastoma." (PMID 39367051, 2024). "However, PHOX2B also has tumor suppressor properties in the final metastatic phase: knockdown of PHOX2B in human neuroblastoma micrometastasis increased the metastatic potential of the cells, which were orthotopically inoculated in nude mice." (PMID 38666930, 2024). "Other factors, in turn, are altered in a tumor-specific manner and may consequently qualify as tumor biomarkers (e.g., GD2 and Phox2B for neuroblastoma)." (PMID 38666930, 2024). "Additionally, mutations in the paired-like homeobox 2B (PHOX2B) and anaplastic lymphoma kinase (ALK) genes have been detected in patients with rare familial neuroblastoma." (PMID 37835497, 2023). "Furthermore, Myocardial Infarction Associated Transcript (MIAT) can promote neuroblastoma by the modulation of MYCN and Paired-like homeobox 2b (PHOX2B) driver genes." (PMID 37888204, 2023). "Moreover, PHOX2B has emerged as a highly reliable immunohistochemical marker for pediatric-type neuroblastoma due to its high sensitivity and specificity when compared to other small round blue cell tumors commonly encountered in childhood." (PMID 38031161, 2023). "Another possible explanation could be that etonogestrel acts on PHOX2B residual cells by decreasing the level of toxic cellular mutant PHOX2B protein, as recently reported in neuroblastoma cell lines." (PMID 36896185, 2023). "Sequencing of ALK mutational hotspots should be performed in neonates presenting with neuroblastoma and hypoventilation without PHOX2B mutations." (PMID 36140661, 2022). "This study reports the presence of a novel de novo ALK germline F1174I mutation in an infant presenting with multifocal neuroblastoma and central hypoventilation in the absence of PHOX2B alterations." (PMID 36140661, 2022). "The adrenergic identity of the ADRN subtype of neuroblastoma cells is maintained by a transcriptional core regulatory circuit (CRC) of predominantly developmental regulators of neurogenesis including PHOX2B, GATA3 and ASCL1, whose expression is further maintained by high levels of MYC or MYCN." (PMID 36263020, 2022). "Neuroblastoma tumors are mixed tumors, composed of an adrenergic component identified by the expression of Phox2b, Hand2, Gata3 and a mesenchymal component (also referred to as a NCC-like component) identified by the expression of Prrx1, Vim, Snai2, Fosl1/2, Jun and others." (PMID 32748156, 2021). "Sphere forming neuroblastomas were mainly composed of Mycn+ and phox2b+ cells." (PMID 33585251, 2020).
neuroblastoma (continued). "While the existence of familial neuroblastoma had been described for decades, it was not until 2004 that the first neuroblastoma predisposition gene, paired-like homeobox 2B gene (PHOX2B), was identified." (PMID 30200332, 2018). "Since 2004, the paired-like homeobox 2B (PHOX2B) gene, encoding a transcription factor crucial for the early steps of autonomous nervous system development, proved to take part in the complexity of the genetic landscape of neuroblastoma." (PMID 29069774, 2017). "Finally, a strong correlation between the effect of drugs in terms of down-regulation of PHOX2B expression and of biological consequences in neuroblastoma cells confirms the role of PHOX2B as a potential molecular target in neuroblastoma." (PMID 29069774, 2017). "Though it has been mainly used so far for its effect in regulating the autophagy process, our HTS results confirm CQ as a specific anti- neuroblastoma agent acting through PHOX2B down-regulation, and therefore indicate CQ as an effective key molecule in neuroblastoma treatment." (PMID 29069774, 2017). "Overall, the results of this study suggest that MMF and CQ could be considered for neuroblastoma therapy, as they displayed specific effects on neuroblastoma cell viability mediated by PHOX2B gene expression down-regulation." (PMID 29069774, 2017). "Based on previous data suggesting PHOX2B overexpression as a possible molecular target for neuroblastoma therapy, we performed two high throughput screenings (HTS) of drugs following a standard drug discovery process, which can be classified into five steps, namely: i." (PMID 29069774, 2017). "However, down-regulation of mature neuronal genes, including PHOX2B, arrested the differentiation of malignant human neuroblastoma SH-SY5Y cells and enhanced their sensitivity to anticancer drugs." (PMID 29069774, 2017). "Therefore, as correct levels of PHOX2B are crucial for a proper neural differentiation, PHOX2B gene expression can be considered a druggable target against neuroblastoma development." (PMID 29069774, 2017). "Moreover, PHOX2B gene dosage is important for the correct development of the sympathetic neuronal system, as shown in a zebrafish model of neuroblastoma where both phox2b knockout and phox2b neuroblastoma associated mutation led to a block of differentiation." (PMID 29069774, 2017). "Accordingly, high expression levels of Phox2B promote neuroblastoma cell proliferation and xenograft tumor growth, while proliferation of undifferentiated Phox2B expressing neuronal progenitors is suggested as a mechanism inducing neuroblastoma development." (PMID 29069774, 2017). "For this reason, we investigated whether PHOX2B down-regulation induced by the three selected drugs could decrease neuroblastoma cell growth by evaluating both apoptosis and cell proliferation." (PMID 29069774, 2017). "Familial neuroblastoma is largely explained by germline mutations in ALK or PHOX2B." (PMID 28545128, 2017). "Further functional investigations carried out on PHOX2B mRNA levels and biological consequences, such as neuroblastoma cell apoptosis and growth, showed that chloroquine and mycophenolate mofetil are most promising agents for neuroblastoma therapy based on down-regulation of PHOX2B expression." (PMID 29069774, 2017). "Moreover, as PHOX2B is overexpresseed in neuroblastoma, these results suggest that, to achieve down-regulation of the PHOX2B protein, it is necessary to select drugs that are very effective in reducing mRNA levels." (PMID 29069774, 2017). "Furthermore, the evaluation of PHOX2B gene expression is currently used to monitor minimal residual disease in neuroblastoma patients." (PMID 29069774, 2017). "PHOX2B promoter methylation leads to PHOX2B inactivation in neuroblastoma tumors and cell lines." (PMID 26840262, 2016). "The main goal of this research was, therefore, to find out whether PHOX2B is functionally involved in shaping the micro-metastatic phenotype of neuroblastoma cells." (PMID 26840262, 2016).
neuroblastoma (continued). "Paired like homeobox 2B (PHOX2B) is a minimal residual disease (MRD) marker of neuroblastoma." (PMID 26840262, 2016). "In the present study we established that PHOX2B functions as a suppressor of neuroblastoma metastasis: The knockdown of PHOX2B in human neuroblastoma micro-metastatic cells increased the tumorigenic and metastatic potential of the cells in orthotopically inoculated nude mice." (PMID 26840262, 2016). "Also, other mutations like PHOX2B and ATRX as well as epigenetic aberrations have been reported in neuroblastoma." (PMID 27036398, 2016). "Taken together this pre-clinical study demonstrates that PHOX2B is a metastasis suppressor, able to inhibit the tumorigenic and metastatic abilities of neuroblastoma cells and that this inhibitory function is likely mediated by the tumor microenvironment via an epigenetic mechanism." (PMID 26840262, 2016). "It shows, however, that PHOX2B restrains the migratory capacity of neuroblastoma cells." (PMID 26840262, 2016). "Furthermore, tumors strongly expressed the neuroblastoma-specific marker genes, dopamine β-hydroxylase (Dbh), tyrosine hydroxylase (Th) and paired-like homeobox 2b (Phox2b), as observed by quantitative PCR (qPCR)." (PMID 25174395, 2015). "The same effect was seen on overexpression of two distinct neuroblastoma-associated frameshift mutations, 676delG and K155X - but not the R100L missense mutation - in the presence of endogenous Phox2b, pointing to their dominant-negative effects." (PMID 23754957, 2013). "PHOX2B plays a key function in the development of neural crest derivatives, and heterozygous mutations cause a complex dysautonomia associating HSCR, Congenital Central Hypoventilation Syndrome (CCHS) and neuroblastoma (NB) in various combinations." (PMID 23342068, 2013). "Notably, PHOX2B is highly expressed in most neuroblastoma cells." (PMID 41578938, 2026). "Additionally, the complex interaction between PHOX2B and other signaling pathways in neuroblastoma suggests that combination therapies may be necessary, which could introduce challenges in terms of optimizing treatment regimens and minimizing toxicity." (PMID 40104501, 2025). "Moreover, tumour morphology, Ki-67 proliferative index (Fig. EV4D,E) and tumour immunohistochemical staining for PHOX2B (neuroblastoma) and CD99 (Ewing sarcoma) remained unchanged between tumours generated from non-bioprinted and bioprinted cells (Fig. 5Bii,Cii)." (PMID 41034452, 2025). "Clinical manifestations have been shown to correlate to the type of PHOX2B mutation identified, such that expansion of the second polyalanine repeat is mainly associated with CCHS, while missense or frameshift mutations are associated with combined CCHS-HSCR-Neuroblastoma." (PMID 36140661, 2022). "Here we report on a patient with multifocal, congenital neuroblastoma in association with clinical features similar to congenital central hypoventilation syndrome with a de novo germline ALK F1174I mutation in the absence of PHOX2B mutation." (PMID 36140661, 2022). "Outside of SCNAs, 108 NB-ASE genes are located in genome regions that are copy neutral across all tumor samples, including PHOX2B which is a target of recurrent germline mutations in neuroblastoma." (PMID 35246212, 2022). "Different heterozygous mutations of PHOX2B are known to cause Congenital Central Hypoventilation Syndrome (CCHS) (OMIM# 209880), a rare disease characterized by impaired ventilator response to hypercapnia and hypoxia, often associated with HSCR and neuroblastomas." (PMID 31767031, 2019). "Furthermore, it has been observed that neuronal differentiation in neuroblastoma is dependent on down-regulation of PHOX2B expression, which confirms that PHOX2B expression may be considered a target in neuroblastoma." (PMID 29069774, 2017).
neuroblastoma (continued). "Therefore, an alteration of PHOX2B levels could interfere with different stages of neuroblastoma development, starting from impaired differentiation of neuronal progenitors in the very early stages to their clonal expansion and tumor invasion." (PMID 29069774, 2017). "PHOX2B proteins also interact with other proteins regulating gene expression and cell signaling, thus accounting, once defective, for not only the respiratory phenotype, but also the development of accompanying disorders such as neuroblastoma and Hirschsprung disease." (PMID 25928806, 2014). "Similarly, TFs linked to neural development including MYCN, PHOX2B, SOX10, and GATA3, drive high-risk neuroblastoma (NB)." (PMID 41228232, 2025). "PHOX2B binds to the ALK gene promoter and activates the Delta-Notch pathway to induce neuroblastoma cell proliferation." (PMID 40104501, 2025). "For example, ALX4 was found to bind the P3 site in human cranial neural crest cells; Phox2a enriched for P3 dimer sites in cortical motor neurons; and PHOX2B predominantly binds to only P3 sites in KELLY, BE2C, and CLBGA neuroblastoma cell lines." (PMID 41279221, 2025). "We were the first to describe paired-like homeobox 2b (PHOX2B) as a highly sensitive and neuroblastoma specific mRNA marker for MRD detection." (PMID 39722049, 2024). "In neuroblastoma, our analysis identified the transcription factors ISL1, HAND2, PHOX2B, PHOX2A, and MYCN as the top five targets critical for the survival of cell lines." (PMID 37297004, 2023). "When compared with the neuroblastoma genes, 7/14 DHFR-positive patients were also positive for PHOX2B and/or CHRNA3." (PMID 37046768, 2023). "GATA2 has been identified as a component of the transcriptional regulatory circuits involving super enhancers in neuroblastoma cells, which also includes GATA3, PHOX2A, PHOX2B, and HAND2." (PMID 36980710, 2023). "The co-occurrence of neuroblastoma and clinical suspicion of CCHS in this patient prompted us to sequence the coding parts of exon 1–3 and flanking splice sites of the PHOX2B gene." (PMID 36140661, 2022). "Specifically, ETO reduces the expression level of PHOX2B and its known target genes (T-cell leukaemia homeobox 2 and DBH) in neuroblastoma cell lines through activation of the nuclear PGR." (PMID 35563209, 2022). "Surprisingly, ASCL1 deletion had little effect on the transcription of CRC gene transcripts in these neuroblastoma cell lines, but the ability of MYC/MYCN and CRC component proteins, PHOX2B and GATA3, to bind to chromatin was compromised." (PMID 36263020, 2022). "The adrenergic CRC consists of an interdependent autoregulatory network that includes HAND2, ISL1, PHOX2B, GATA3, ASCL1, and TBX2 and is essential to drive the expression of MYCN and to facilitate the growth and survival of MYCN-amplified neuroblastoma cells." (PMID 34669465, 2021). "Genes known to be specifically expressed in neuroblastoma, such as HAND2, PHOX2B, and DBH, were homogeneously expressed across all samples, indicating that the proportion of mRNA derived from neuroblastoma cells was equally distributed between each sample." (PMID 34815394, 2021). "Gene expression levels for the adrenergic neuroblastoma CRC members—MYCN, HAND2, ISL1, PHOX2B, GATA3, ASCL1, and TBX2—were assayed by quantitative RT-PCR at 1, 3, and 6 days after treatment with 5 μM ATRA." (PMID 34669465, 2021). "ADRN-type neuroblastoma, showing sympathetic noradrenergic identity, was characterized by CRC modules formed by several transcription factors, such as HAND2, PHOX2B, and GATA3, leading to high expression of these genes." (PMID 33465163, 2021). "ChIP-seq for the PHOX2B, HAND2, and GATA3 TFs in the neuroblastoma CLB-GA cell line confirmed that binding regions for these three TFs corresponded to the H3K27ac peaks and SEs of the NOR identity." (PMID 34200747, 2021).
neuroblastoma (continued). "For example, the expression footprint of six neuroblastoma-related genes (ALK, BIRC5, CCND1, MYCN, NTRK1 and PHOX2B) have been used to differentiate neuroblastoma molecular subtypes." (PMID 34842635, 2021). "Further, different mRNA markers are being explored for MRD detection in blood (PHOX2B, TH, DDC, DBH, and CHRNA3) and bone marrow (PHOX2B, TH, DDC, CHRNA3, and GAP43) from neuroblastoma patients." (PMID 31897843, 2020). "Here, we report the first examination of PHOX2B in 1470 HSCR and 469 neuroblastoma patients with matched healthy controls." (PMID 30799307, 2019). "The combined signature of five markers (CHGA, DCX, DDC, PHOX2B, and TH) expression in BM and PB was correlated with PFS of relapsed/refractory neuroblastoma." (PMID 31214500, 2019). "Phox2b mutations cause congenital central hypoventilation syndrome, which serves as the predisposition for ganglioneuroma (GN), ganglioneuroblastoma (GNB), and NB." (PMID 31867574, 2019). "Among these markers, PHOX2B was identified as the most specific and sensitive marker for qPCR-based MRD detection in neuroblastoma patients." (PMID 31214500, 2019). "Regulatory elements controlling ASCL1 expression are bound by LMO1, MYCN and the transcription factors GATA3, HAND2, PHOX2B, TBX2 and ISL1—all members of the adrenergic (ADRN) neuroblastoma core regulatory circuitry (CRC)." (PMID 31819055, 2019). "Linking both PHOX2B and ALK biology, some neuroblastoma cell lines, inducing overexpression of PHOX2B, led to increased ALK expression." (PMID 30200332, 2018). "PHOX2B, a transcription factor and a specific and sensitive bio-marker for MRD in neuroblastoma patients, is highly expressed in micro-metastatic neuroblastoma cells (MicroNB), but not, or significantly less in macro-metastatic cells (MacroNB)." (PMID 26840262, 2016). "We next tested whether we could successfully activate and repress PHOX2B expression and detected robust activation by targeting dCas9-VPR at its promoter in the neuroblastoma-derived cell line SHSY-5Y." (PMID 40930101, 2025). "Unlike Phox2B, which is well described in the context of neuroblastoma, it is not possible to clearly infer the potential actions of Nrf2 and NF-κB in the molecular machinery of this cancer type." (PMID 38666930, 2024). "The use of 5 ́-aza may also be considered in neuroblastoma treatment due to its regulatory effect on the activity of both KEAP-1 and PHOX2B promoters." (PMID 38666930, 2024). "The results showed significant surface PHOX2B pMHC in neuroblastoma cells and not in HLA-matched controls, which suggested that these reagents have the potential to be used to assess the presence of antigen in biopsied tissue samples." (PMID 37938771, 2023). "Histologically, the primary tumor biopsy did not express common neuroblastoma markers (negative for PHOX2B and TH, but positive for Chromogranin A)." (PMID 37664065, 2023). "In 4 patients with clinically-proven metastatic disease in their bone marrow aspirates (NB4, NB17, NB19, NB25), DTCs stained positive for neuroblastoma immunohistochemical markers PHOX2B and TH, and DTC-enriched fractions from BMAs also expressed elevated levels of PHOX2B and TH on RT-qPCR." (PMID 36176417, 2022). "Interestingly, both ETO and PG administration in neuroblastoma cell lines, expressing both PHOX2B and nuclear PGR, induced a direct reduction in PHOX2B expression, as well as reduced promoter activity of PHOX2B target genes." (PMID 35563209, 2022). "To further test the hypothesis that ASCL1 regulates chromatin accessibility of these transcription factors, we utilised publicly available PHOX2B and GATA3 ChIP-seq datasets in parental BE2C and Kelly neuroblastoma cell lines." (PMID 36263020, 2022). "Notably, this identified motifs with high similarity to the known binding motifs of several neuroblastoma core regulatory circuit transcription factor motifs including HAND2, GATA3 and PHOX2B." (PMID 36263020, 2022).